ALK (ALK receptor tyrosine kinase)
Diseases named in the same sentence as ALK in open-access papers (continued):
Sharing a sentence is not in itself a finding about the gene and the disease.
renal cell carcinoma (52 papers, 2010 to 2026). "Anaplastic lymphoma kinase rearrangement-associated renal cell carcinoma (ALK-RCC) is an extremely rare tumor and ALK-RCC that mimics mucinous tubular and spindle cell carcinoma (MTSCC) has been very reported only in one instance." (PMID 35718773, 2022). "The tumor was thus correctly diagnosed as ALK rearrangement-associated renal cell carcinoma (ALK-RCC)." (PMID 35718773, 2022). "Anaplastic lymphoma kinase rearrangement-associated renal cell carcinoma (ALK-RCC) is a very rare tumor that accounts for <1% of all renal neoplasms." (PMID 35718773, 2022). "Renal cell carcinoma (RCC) associated with anaplastic lymphoma kinase (ALK) gene rearrangements (ALK-RCC) is currently considered an “emerging or provisional” tumor entity by the last World Health Organization classification published in 2016." (PMID 35409355, 2022). "Several groups had continuously reported translocation-associated renal cell carcinomas (ALK-tRCCs)." (PMID 31627758, 2019). "Translocation-associated renal cell carcinoma involving ALK (ALK-tRCC) is a rare subtype of adult renal cell carcinoma (RCC) reported in recent years." (PMID 31627758, 2019). "Anaplastic lymphoma kinase (ALK)-rearranged renal cell carcinoma (ALK-RCC) is an extremely rare subtype of RCC, accounting for less than 1% of all cases." (PMID 41883969, 2026). "Among the differential diagnoses that should be considered are: collecting duct carcinoma, malignant rhabdoid tumor, urothelial carcinoma, renal cell carcinoma with vinculin-ALK translocation-anaplastic lymphoma kinase (VCL-ALK), among others." (PMID 40777608, 2025). "It has been proposed that VCL-ALK RCC developed in a 14-year-old girl with the sickle cell trait in ALK-rearranged renal cell carcinoma." (PMID 37056387, 2023). "ALK translocations are also present in diffuse large B cell lymphomas, breast, and renal cell carcinomas at low frequency." (PMID 30813562, 2019). "In this regard, ALK-CNG has been reported in the 10 % of renal cell carcinoma patients and the presence of more than 5 copies of the ALK gene was significantly associated with high tumor size, nuclear grade and worse 10-years survival rate." (PMID 27561692, 2016). "Gene fusions involving clathrin heavy chain (CLTC) have been described in various leukemias (CLTC/ALK) and in renal cell carcinoma (CLTC/TFE3)." (PMID 23637631, 2013). "Although ALK-RCC is currently considered an "emerging/provisional" type of renal cell carcinoma in the 2016 World Health Organization classification, the Genitourinary Pathology Society recently proposed categorizing ALK-RCC as a "novel entity" based on an accumulation of studies." (PMID 35718773, 2022). "For unclassified renal cell carcinoma cases, it is advisable to perform next-generation sequencing (NGS) and ALK testing, as these analyses may identify actionable mutations or alterations that can guide targeted therapeutic strategies and improve clinical outcomes." (PMID 39858107, 2025). "The diagnosis of ALK-RCC based on histological features alone is difficult, as its heterogeneous appearance can mimic various renal cell carcinomas." (PMID 39205743, 2024). "In the phase II eligible population, the ORR was 86% among 14 patients with ROS1-rearranged disease (all but one with NSCLC), and an ORR of 57% among seven patients with ALK-rearranged tumors, including NSCLC, renal cell carcinoma, and CRC." (PMID 38938274, 2024). "Aberrant activation ALK has been linked to many types of human cancer, such as anaplastic large-cell non-Hodgkin’s lymphoma (ALCL), non-small-cell lung cancer (NSCLC), neuroblastoma, renal cell carcinoma (RCC), and thyroid and breast cancer." (PMID 36986673, 2023). "Immunohistochemistry showed ALK, EMA, and AE1/AE3 immunoreactivity suggesting ALK-rearranged renal cell carcinoma (Case 1) and coexpression of keratin, EMA, synaptophysin, and chromogranin-A, suggesting neuroendocrine neoplasm (Case 2)." (PMID 34228212, 2022).
renal cell carcinoma (continued). "Low-level ALK copy number gain is relatively common in some tumor types, e.g., in alveolar rhabdomyosarcoma, in NSCLC, and in up to 10% of renal cell carcinomas." (PMID 33237469, 2021).
sarcoma (52 papers, 2011 to 2025). A usually aggressive malignant neoplasm of the soft tissue or bone. "This is the first description tracking the development of resistance mutations in a patient with non‐myofibroblastic sarcoma therefore adding to what is currently a limited body of evidence in non‐lung ALK‐rearranged cancers." (PMID 39188081, 2024). "The fourth gene deregulated in TFCP2-rearranged sarcoma, besides ALK, CDKN2A, and MTAP, is TERT, encoding the catalytic component of the telomerase complex that protects dividing cells from progressive telomere shortening, subsequent senescence, and malignant transformation." (PMID 38168093, 2024). "However, immunohistochemistry for CD30 and T-cell markers is not typically performed as part of the diagnostic work up of sarcomas, resulting in the under recognition of sarcomatoid ALK- ALCL." (PMID 34572893, 2021). "Taken together, TFCP2-rearranged sarcoma likely represents a separate entity characterized by distinct transcriptional and DNA methylation profiles, an unusual degree of genomic instability, truncated ALK variants, ALK and TERT overexpression, and recurrent CDKN2A/MTAP co-deletions." (PMID 38168093, 2024). "As ALK alterations commonly co-occur in these sarcomas, two of our patients were treated with ALK inhibitors, with initial, although short-lived, benefits." (PMID 40361368, 2025). "This case highlights the importance of early presentation and timely diagnosis using next generation sequencing to facilitate targeted therapy for ALK‐rearranged chest wall sarcomas and improve patient outcomes." (PMID 40904239, 2025). "Anaplastic lymphoma kinase (ALK) rearrangements are rare in non‐myofibroblastic sarcoma and there is limited data on the efficacy of ALK tyrosine kinase inhibitors (TKIs) and mechanisms of resistance in these patients." (PMID 39188081, 2024). "The frequent overexpression of wildtype (WT) ALK and/or ALK variants suggested that these events are critical for the pathogenesis of TFCP2-rearranged sarcoma." (PMID 38168093, 2024). "Despite the limited number of cases, the observations in patients and ex vivo and in vitro drug response data support that ALK inhibitors should be further explored in FUS/EWSR1-TFCP2 sarcoma." (PMID 38168093, 2024). "In conclusion, this ALK rearrangement in an osteosarcoma is a rare finding that demonstrates acquired RTK alterations are possible in sarcoma." (PMID 38096470, 2023). "ALK expression is common in several translocation sarcomas including angiomatoid fibrous histiocytoma and rhabdomyosarcoma." (PMID 34228212, 2022). "Anaplastic lymphoma kinase (ALK) is a tyrosine kinase oncoprotein expressed by several tumors, including sarcomas." (PMID 34722239, 2021). "As expected, lung tumors with driver fusions harbored mostly EML4/ALK fusions, sarcomas were driven mostly by EWSR1-related and PAX3/FOXO1 fusions, while hematologic malignancies with a spectrum of BCR/ABL1, KMT2A-related, and IGH/MYC fusions." (PMID 33889297, 2021). "It was gradually off-label in the treatment of inoperable sarcomas that are carried with ALK fusions since the first case of inflammatory myofibroblastic sarcoma (IMT) with the ALK rearrangement showed a favorable response to crizotinib." (PMID 34722239, 2021). "Surgical resection remains the mainstay of treatment for localized ALK-positive sarcoma and sarcomatous malignancies." (PMID 34722239, 2021). "Findings from this analysis indicated that crizotinib-based palliative treatment regimens improved outcomes in patients with ALK-positive sarcoma and sarcomatoid malignancies." (PMID 34722239, 2021). "Owing to the low incidence of ALK-fusion sarcoma and sarcomatoid malignancies, most of the available data are case reports with detailed molecular profiles." (PMID 34722239, 2021).
sarcoma (continued). "ALK-positive sarcoma is predominantly seen in pediatric or middle-aged patients, with only 2 patients older than 60-years in our cohort of 33 cases." (PMID 34722239, 2021). "Although limited by sample size, our pooled analysis showed up to 86.7% efficacy of crizotinib in ALK-positive sarcoma or sarcomatoid malignancies with equal effectiveness in both adult and pediatric patients." (PMID 34722239, 2021). "These sarcoma subtypes were chosen as they are known to harbor specific alterations that result in ALK and/or MET activation." (PMID 31665941, 2019). "Sarcoma therapy will likely involve agents that target PTEN/ALK/MTOR pathway members alone, in combination, or/and with other oncogenic pathways associated with or without standard cytoreductive chemotherapy." (PMID 31416195, 2019). "There was also a marked reduction in phosphorylation of RTKs such as Axl and ALK which have also been reported as potential driver kinases in sarcoma." (PMID 26675259, 2016). "The accuracy of the ALK test to distinguish IMTs from sarcomas and other soft tissue tumours was determined by the area under the curve (AUC) of receiver operating characteristic (ROC); the AUC value was 0.95 (95% CI 0.93–0.97)." (PMID 25910080, 2015). "Anaplastic lymphoma kinase (ALK) is overexpressed in IMTs and ALCLs compared with normal tissue and other soft tissue tumours, particularly sarcomas." (PMID 25910080, 2015). "The mean of 3′-ALK expression of ALK+ lung tumor is approximately 500, whereas this reached approximately 3000 in the sarcoma." (PMID 24406431, 2014). "MDM2 co-expression in our case suggested sarcoma initially, necessitating ALK-FISH confirmation." (PMID 40917711, 2025). "Additionally, although rare, several reports describe successful ALK‐targeted therapy in sarcomas with ALK fusions." (PMID 40904239, 2025). "Together, these data showed that FUS/EWSR1-TFCP2 transcriptionally activates a core set of genes that include ALK and regulators of muscle physiology, which together may play a role in sarcoma development." (PMID 38168093, 2024). "To date, two patients with FUS/EWSR1-TFCP2 sarcoma who received ALK inhibitors have been reported." (PMID 38168093, 2024). "Crizotinib treatment in ALK-fusion sarcoma and sarcomatous malignancies." (PMID 34722239, 2021). "Therefore, we aim to provide a systematic review of the available data on the therapeutic effects of crizotinib in ALK-positive sarcoma and sarcomatoid malignancies." (PMID 34722239, 2021). "The morphology of an inflammatory pseudotumor is diverse and some cases may show significant atypia to consider the possibility of a high-grade sarcoma, and for the purpose of this review also of sarcomatoid ALK- ALCL." (PMID 34572893, 2021). "The CREATE trial is an example of a biomarker-driven basket trial, leveraging on the demonstrated biological activity of crizotinib in preclinical work and applying that to sarcoma subtypes with known genetic alterations resulting in the upregulation of ALK and/or MET." (PMID 31665941, 2019). "Thus, ALK likely contributes to the development of FUS/EWSR1-TFCP2 sarcomas and could, in principle, be a therapeutic target." (PMID 38168093, 2024). "These TKIs include Anaplastic Lymphoma Kinase (ALK) inhibitors, such as crizotinib and alectinib, for ALK fusion‐positive sarcomas and TRK inhibitors, such as larotrectinib and entrectinib, for NTRK fusion‐positive sarcomas." (PMID 40755265, 2025). "Finally, our findings suggest that patients with TFCP2-rearranged sarcomas, which are refractory to conventional chemotherapy, may benefit from combination treatments that include platinum derivatives, ALK inhibitors, and, in the case of CDKN2A/MTAP co-deletions, drugs targeting PRMT5." (PMID 38168093, 2024). "In a recent large study of sarcoma, CGP identified potentially actionable kinase fusions (including NTRK1‐3, ALK, BRAF, FGFR1‐4, RET, and ROS1) in 2.6% of patients." (PMID 38925616, 2024).
sarcoma (continued). "This is the case for subtypes with available targeted therapies, such as NTRK-rearranged sarcomas, IMT with ALK fusion, and GIST." (PMID 39001377, 2024). "These included ALK, BRAF, FGFR1–4, NTRK1–3, RET, and ROS1 kinase fusions in a wide range of sarcoma histologies, including IMT (62.1%), MPNST (4.9%), UPS of bone (4.3%), extraskeletal osteosarcomas (4%), UPS (3.6%), sarcoma NOS (3.8%), and LMS (1.9%)." (PMID 35705558, 2022). "Crizotinib, which inhibits c-Met and ALK, is also being tested in clinical trials (Clinical Trial Identifier NCT01524926) for sarcoma." (PMID 26675259, 2016). "Aberrant ALK and IGF-1R signaling have been demonstrated to contribute to oncogenic transformation in pediatric sarcomas and the involvement of IGF-1R signaling in resistance to HDACi was reported in NSCLC." (PMID 26571493, 2015). "There are case reports of ALK positive inflammatory myofibroblastic tumour responding to lorlatinib, but no documented cases of response to lorlatinib in other sarcoma subtypes." (PMID 39188081, 2024). "Overall, to our knowledge, the findings of our case represent the first actionable ALK rearrangement in osteosarcomas, as well as its acquired status, which previously has not been established in sarcomas." (PMID 38096470, 2023). "Unlike kinase fusions present in other sarcomas involving NTRK3 or ALK, however, FOXO1 fusions lack an enzymatic, readily druggable activity." (PMID 36282590, 2022). "Reports of use of other multi-kinase inhibitors in sarcoma such as imatinib have not been very encouraging or restricted to a smaller patient sub-population such as use of crizotinib in ALK driven tumors." (PMID 26675259, 2016). "Second, there is still a concern that included ALK-negative IMTs in this study might belong to unclassified low grade sarcoma or other tumor, although we thoroughly examined included cases with all available ancillary tests and excluded the differential diagnoses." (PMID 29163763, 2017). "Despite the prevalence of ALK alterations and overexpression, most TFCP2 fusion sarcoma patients treated with ALK inhibitors have not responded well." (PMID 40361368, 2025). "For example, not all BCOR-rearranged sarcomas are positive for BCOR on IHC, and a subset of IMTs are negative for ALK on IHC because they harbor alternative ROS1 or RET gene fusions instead of an ALK fusion." (PMID 38137051, 2023).
Histiocytosis (48 papers, 2019 to 2026). An excessive number of histiocytes (tissue macrophages). "In such cases, it may be classified into the ECD category of the L group, particularly when accompanied by MAPK-activating mutations, or classified as ALK-positive histiocytosis when carrying ALK immunoreactivity and/or ALK gene rearrangement." (PMID 38713245, 2024). "When invading the CNS, ALK-positive histiocytosis can cause headache, vomiting, and seizures." (PMID 35359354, 2022). "Summary of clinical characteristics and outcomes in published cases of mammary ALK‐positive histiocytosis." (PMID 41550401, 2026). "Our case is notable for older age at diagnosis, isolated intramedullary involvement, and radioresistance but later marked targeted-therapy response, thus furthering the understanding of the spectrum of ALK-positive histiocytosis biology." (PMID 41635628, 2026). "We herein report a case of ALK-positive histiocytosis harboring a TFG-ALK fusion gene with durable response to alectinib." (PMID 40700600, 2025). "Histiocytic neoplasms: this category includes a variety of disorders such as juvenile xanthogranuloma (JXG), Erdheim-Chester disease (ECD), Rosai-Dorfman disease (RDD), ALK-positive histiocytosis, and histiocytic sarcoma." (PMID 40620437, 2025). "The novelty of this genetic alteration and the lack of knowledge about its potential effects on the clinical aspects of ALK-positive histiocytosis highlight the importance of ancillary molecular testing, when available." (PMID 40361876, 2025). "Even though ALK::TFG fusions are rare events in histiocytosis, their identification and targeted ALK inhibitor therapy dramatically improved the patient’s quality of life." (PMID 38833619, 2025). "Now, ALK-positive histiocytosis is a new entity in the 5th edition of the World Health Organization classification of haematolymphoid tumours: myeloid and histiocytic/dendritic neoplasms." (PMID 39998733, 2025). "ALK-positive histiocytosis is characterized by the presence of ALK fusions (most frequently KIF5B::ALK) and a remarkable response to ALK inhibitor therapy." (PMID 40700600, 2025). "ALK-positive histiocytosis is a distinct form of histiocytosis that has the potential to be treated with an ALK inhibitor." (PMID 40700600, 2025). "ALK-positive histiocytosis is a rare condition that can affect multiple systems in infants and adults." (PMID 40700600, 2025). "The present study reports a pediatric case of ALK-positive histiocytosis with DCTN1::ALK gene rearrangement." (PMID 40361876, 2025). "Recent studies have demonstrated that patients with ALK-positive histiocytosis respond favorably to ALK inhibitor therapies, leading to significant clinical improvements." (PMID 39998733, 2025). "The combination of histological findings, immunophenotype, and genetic changes established the diagnosis of ALK-positive histiocytosis." (PMID 40700600, 2025). "Anaplastic lymphoma kinase (ALK)-positive histiocytosis is a rare histiocytic neoplasm characterized by ALK rearrangements within histiocytes." (PMID 39998733, 2025). "The third group is called “histiocytic neoplasms” and includes “juvenile xanthogranuloma,” “Erdheim‐Chester disease,” “Rosai‐Dorfman disease,” “ALK‐positive histiocytosis,” and “histiocytic sarcoma “." (PMID 40938275, 2025). "ALK-positive histiocytosis is an extremely recent discovery with the first case being reported 14 years ago." (PMID 38376733, 2025). "The prognosis for ALK-positive histiocytosis varies depending on the extent of disease involvement, the affected organs, and the treatment response." (PMID 39998733, 2025). "KIF5B has been shown to be the most common fusion-partner gene in ALK-positive histiocytosis, whereas CLTC, TPM3, EML4, and TFG have only been infrequently recorded." (PMID 40700600, 2025). "ALK-positive histiocytosis is a rare cancer that was first described in 2008 as a systemic histiocytic disorder that can affect multiple organs." (PMID 40700600, 2025).